CALR (calreticulin)
Diseases named in the same sentence as CALR in open-access papers (continued):
Sharing a sentence is not in itself a finding about the gene and the disease.
myeloproliferative neoplasm (continued). "The discovery of mutated Calreticulin (CALR) in myeloproliferative neoplasms (MPN) has provided proof of clonality, diagnostic importance and influence on prognosis of this pathology." (PMID 32929772, 2021). "Calreticulin plays an accessory role in immunoproteasome activity through its function as a chaperone in the endoplasmic reticulum, but mutations in this gene are frequently implicated in myeloproliferative disorders such as essential thrombocythemia or older patients with primary myelofibrosis." (PMID 34225749, 2021). "Mutations in JAK2, Myeloproliferative Leukemia Virus (MPL), or Calreticulin (CALR) are detected in more than 80% of myeloproliferative neoplasm (MPN) patients, and these mutations are thought to play a significant role in the pathogenesis of MPN1–7." (PMID 30926777, 2019). "In 2013, mutations in exon 9 of the calreticulin gene (CALR) were discovered in ~ 80% of JAK2wt myeloproliferative neoplasm patients (MPN)." (PMID 30001747, 2018). "We initially focused on identifying HLA class I neoepitopes derived from calreticulin (CALR) exon 9 mutations, found in ~ 80% of JAK2wt myeloproliferative neoplasms (MPN)." (PMID 30001747, 2018). "This is the first report to show an association between CALR mutations in patients with myeloproliferative neoplasms (MPN) and the NAP score." (PMID 27504244, 2016). "Somatic frameshift mutations in exon 9 of calreticulin (CALR) have been identified in a large proportion of JAK2- or MPL-negative myeloproliferative neoplasm (MPN) patients, including those with primary myelofibrosis (PMF) and essential thrombocythemia (ET)." (PMID 26377485, 2016). "Using exome sequencing, calreticulin (CALR) frameshift mutations were discovered in myeloproliferative neoplasms (MPN) and shown to be restricted to essential thrombocythemia (ET) and primary myelofibrosis (PMF)." (PMID 27177927, 2016). "The presence of mutations in the JAK2, CALR, and MPL genes is essential for the diagnosis of myeloproliferative neoplasms." (PMID 39960584, 2026). "Screening for underlying mutations is mandatory, including a myeloproliferative neoplasm genetic panel assessing for JAK2V617F, CALR, and MPL 515 mutations, given their strong association with this group of disorders." (PMID 41393693, 2025). "Myelofibrosis (MF) is a myeloproliferative neoplasm that is accompanied by driver JAK2, CALR, or MPL mutations in more than 90% of cases, leading to constitutive activation of the JAK–STAT pathway." (PMID 40062529, 2025). "Many studies and the revised WHO criteria have shown that the JAK2 V617F, CalR, and MPL gene mutations are crucial for the diagnosis of chronic myeloproliferative neoplasms." (PMID 40572650, 2025). "More than a decade after its discovery, advances have been made in understanding the oncogenic role of mutant CALR in BCR::ABL1-negative myeloproliferative neoplasms (MPNs)." (PMID 41228192, 2025). "Six patients had mutations in driver genes of myeloproliferative neoplasms (MPNs) (JAK2 n = 5 (4%), CALR n = 1 (1%))." (PMID 41008838, 2025). "Consistently, the French Intergroup on Myeloproliferative Neoplasms (FIM) reported a decrease in the JAK2 allele burden of more than 50% in more than half of the patients, while the CALR remained stable." (PMID 41463191, 2025). "Primary myelofibrosis is a clonal myeloproliferative disorder characterized by fibrous tissue deposits in the bone marrow, commonly associated with JAK2, CALR, or MPL mutations." (PMID 39807111, 2025). "Myeloproliferative neoplasms (MPNs) encompass a diverse group of hematologic disorders driven by mutations in JAK2, CALR, or MPL." (PMID 38308077, 2024). "In previous research, we created a C. elegans model with homozygous mutations in calreticulin similar to those found in patients with essential thrombocythemia (ET) and primary myelofibrosis (PMF), two myeloproliferative neoplasms (MPNs)." (PMID 39519157, 2024).
myeloproliferative neoplasm (continued). "Primary myelofibrosis (PMF) is a rare chronic myeloproliferative disorder that is commonly associated with Janus kinase 2 (JAK-2), calreticulin (CALR), or thrombopoietin receptor (MPL) mutations." (PMID 39759619, 2024). "Primary myelofibrosis (PMF) is an uncommon chronic myeloproliferative disorder that is commonly associated with Janus kinase 2 (JAK-2), calreticulin (CALR), or thrombopoietin receptor (MPL) mutations." (PMID 39759619, 2024). "Primary myelofibrosis (PMF) is a type of myeloproliferative neoplasm characterized by the clonal proliferation of stem cells, often accompanied by mutations in Janus kinase 2 (JAK2), calreticulin (CALR), or myeloproliferative leukemia (MPL) genes." (PMID 38983933, 2024). "Therapeutic cancer vaccination against mutant calreticulin (CALR) in patients with CALR-mutant (CALRmut) myeloproliferative neoplasms (MPN) induces strong T-cell responses against mutant CALR yet fails to demonstrate clinical activity." (PMID 37662956, 2023). "The interaction between CALR and MPL plays a pivotal role in the regulation of thrombopoietin receptor MPL and has been associated with the pathogenesis of myeloproliferative neoplasms (MPNs)." (PMID 38132435, 2023). "Myelofibrosis (MF) is a myeloproliferative neoplasm characterized by mutations (most frequently in JAK2, CALR, or MPL), burdensome symptoms, splenomegaly, cytopenia, and shortened life expectancy." (PMID 36786879, 2023). "In myeloproliferative neoplasms, frameshift mutants of calreticulin turn into rogue cytokines by inducing constitutive activation of the Thrombopoietin Receptor (TpoR)." (PMID 37019903, 2023). "Despite discovery of the JAK2, CALR and MPL driver mutations, the molecular etiology of Myeloproliferative Neoplasms (MPN) remains incompletely understood." (PMID 36709354, 2023). "From these, 81% were diagnosed with myeloproliferative disease and 76% carried driver mutations JAK2, CALR, or MPL." (PMID 36698617, 2023). "Regarding the myeloproliferative disorders, it is known that JAK2, CALR, and MPL genes, which are usually associated with MPN disorders such as PMF, PV, and essential thrombocythemia (ET), have to be absent in MDS/MPN with neutrophilia." (PMID 37370785, 2023). "Despite the low clinical suspicion of a myeloproliferative disorder, due to normal blood counts and associated HCV cirrhosis, screening for MPN drivers was employed and identified a type 1 CALR mutation." (PMID 37841434, 2023). "Most cases of myeloproliferative neoplasm are known to harbour driver mutations JAK2, MPL, or CALR in a mutually exclusive manner." (PMID 35237453, 2022). "Clinicopathological characteristics of myeloproliferative neoplasm cases with JAK2 and CALR Mutational status with CAL2IHC." (PMID 34514582, 2022). "In 2013, CALR mutations were first identified as driver mutations in myeloproliferative neoplasm (MPN) and were found in 70–80% of patients with JAK2 V617F-negative essential thrombocythemia (ET) and primary myelofibrosis (PMF), with characteristic clinical findings." (PMID 36359414, 2022). "Recent analysis of CALR fragments in myeloproliferative disease suggests an immunosuppressive influence of extracellular CALR." (PMID 35982973, 2022). "The most frequent molecular mutation present in myeloproliferative neoplasms is the JAK2V617F mutation present in more than 95% of PV patients and 50–60% of ET and PMF patients, followed by CALR mutations and MPL mutations, respectively." (PMID 34831257, 2021). "Somatic mutations in JAK2, calreticulin, and MPL genes drive myeloproliferative neoplasms (MPN), and recent technological advances have revealed a heterogeneous genomic landscape with additional mutations in MPN." (PMID 34680185, 2021). "These myeloproliferative neoplasms are characterized by hyperactivation of janus kinase 2 (JAK2)-signaling as a result of mutations in three specific genes: JAK2, calreticulin (CALR), and myeloproliferative leukemia virus (MPL)." (PMID 34831257, 2021).
myeloproliferative neoplasm (continued). "Frameshifts in the Calreticulin (CALR) exon 9 provide a recurrent driver mutation of essential thrombocythemia (ET) and primary myelofibrosis among myeloproliferative neoplasms (MPNs)." (PMID 33785036, 2021). "Mutations in these three genes (JAK2, CALR and MPL) underlie nearly all the three myeloproliferative diseases, and the presence of one or other in ET and MF has prognostic significance." (PMID 35844697, 2021). "CALR alongside JAK2 and MPL mutations are included as major diagnostic criteria for PMF by the World Health Organization (WHO) classification of myeloproliferative neoplasms." (PMID 32842500, 2020). "Recent data demonstrated that the TPO receptor (MPL) is essential for the development of CALR mutant-driven Myeloproliferative Neoplasms (MPNs)." (PMID 31332222, 2019). "The objective of this review is to characterize studies on BCR-ABL1-negative chronic myeloproliferative neoplasms and to compare the frequency of JAK2, MPL and CALR mutations in PV, ET and PMF." (PMID 31208359, 2019). "The hallmark of BCR-ABL1-negative myeloproliferative neoplasms (MPNs) is the presence of a driver mutation in JAK2, CALR, or MPL gene." (PMID 31106152, 2019). "Primary Myelofibrosis (PMF) is a myeloproliferative disorder associated with JAK2V617F, Calreticulin (CALR) indels, and MPLW515L/K mutations activating the tyrosine kinase JAK2 and its downstream signaling pathway." (PMID 31369569, 2019). "Still, the Italian Collaborative Group for Myeloproliferative Disorders showed that when analyzing 404 patients with either ET or pre-fibrotic PMF, CALR mutations were more frequent in pre-fibrotic PMF than in ET (35·8 vs. 17·8%, P < 001)." (PMID 31555600, 2019). "In myeloproliferative neoplasms the JAK2 and CALR mutations has proven to be immunogenic neo-antigens and thus possible targets for peptide vaccination." (PMID 30327655, 2018). "CALR is involved in the etiology not only of myeloproliferative disorders but also in that of many other cancers." (PMID 29218307, 2017). "Erythroid cells from JAK2V617F myeloproliferative disorders express cell-surface levels of CALR similar to those expressed by normal cells." (PMID 29218307, 2017). "The presence of acquired mutations within the JAK2, CALR, and MPL genes in the majority of patients with myeloproliferative neoplasms (MPN) affords the opportunity to utilise these mutations as markers of minimal residual disease (MRD)." (PMID 27840830, 2016). "Somatic calreticulin (CALR), Janus kinase 2 (JAK2), and thrombopoietin receptor (MPL) mutations essentially show mutual exclusion in myeloproliferative neoplasms (MPN), suggesting that they activate common oncogenic pathways." (PMID 27177927, 2016). "Clonal proliferation in myeloproliferative neoplasms (MPN) is driven by somatic mutations in JAK2, CALR or MPL, but the contribution of inherited factors is poorly characterized." (PMID 25849990, 2015). "Myeloproliferative neoplasms, polycythemia vera, essential thrombocytosis, and primary myelofibrosis are a unique group of clonal hematopoietic stem cell neoplasms that share somatic, gain-in-function driver mutations in JAK2, CALR, and MPL." (PMID 39598101, 2024). "Specifically, CALR driver mutations has been described in myeloproliferative disorders but have not yet been associated to other hematological neoplasia." (PMID 38035116, 2023). "Under pathological conditions, myeloproliferative neoplasms (MPNs), a mutant form of the glycan-dependent molecular chaperone CALR (CALRmut), bind to the immature sugar chain of MPL in the endoplasmic reticulum and then translocate to the cell membrane to form a complex with functional MPL5–7." (PMID 36433967, 2022). "Myeloproliferative neoplasms are characterized by mutations in JAK2, MPL and CALR genes." (PMID 33317584, 2020). "Calreticulin (CALR) gene mutations are currently recommended as biomarkers in diagnosis of patients with myeloproliferative neoplasms (MPN) with Jak2 V617F negative phenotype." (PMID 31248375, 2019).
myeloproliferative neoplasm (continued). "Genetic impairment of CALR gene has been identified in myeloproliferative neoplasms (MPNs)." (PMID 31717602, 2019). "Therefore, the objective of this review is to characterize the studies of BCR-ABL1-negative chronic myeloproliferative neoplasms and to compare the frequency of JAK2, MPL and CALR mutations in PV, ET and PMF." (PMID 31208359, 2019). "In this study, we focus on CALR, since several studies have revealed a connection between disruption of CALR function and various malignancies including myeloproliferative disorders, osteocarcoma, ovarian and non-small cell lung cancer, breast cancer, and Glioblastoma (GBM)." (PMID 29443896, 2018). "Most myeloproliferative neoplasm (MPN) patients lacking JAK2 mutations harbour somatic CALR mutations that are thought to activate cytokine signalling although the mechanism is unclear." (PMID 27740635, 2017). "By contrast with myeloproliferative neoplasms, driver mutations in CALR have not been associated with other hematological or solid tumors as yet." (PMID 29218307, 2017). "Mutations in JAK2, MPL and CALR are highly relevant to the Philadelphia chromosome (Ph)-negative myeloproliferative neoplasms (MPNs)." (PMID 25023898, 2014). "Gene panel studies showed variants in TET 2, CALR (type 2), and DNMT3 A, consistent with myeloproliferative neoplasm (MPN)." (PMID 41464542, 2025). "Testing for the most common chronic myeloproliferative neoplasm-associated mutations, such as Janus kinase 2 (JAK2), Calreticulin (CALR), Myeloproliferative leukemia virus oncogene (MPL) genes, and performing a bone marrow biopsy may also aid in the diagnostic process." (PMID 40130200, 2025). "Essential thrombocythaemia (ET) is one of four chronic myeloproliferative neoplasms (MPN), characterised by clonal thrombocytosis; approximately 85% of patients will have a pathognomonic driver mutation at presentation—JAK-2 (about 50%), CALR (about 30%) or MPL (about 5%)." (PMID 41464542, 2025). "The classical BCR::ABL1-negative myeloproliferative neoplasms such as polycythemia vera (PV), essential thrombocythemia (ET), and myelofibrosis (MF) are clonal diseases with the presence of characteristic “driver mutations” in one of the genes: JAK2, CALR, or MPL." (PMID 37745842, 2023). "Myeloproliferative neoplasms (MPN) are characterized by uncontrolled expansion of myeloid cells, disease‐related mutations in certain driver‐genes including JAK2, CALR, and MPL, and a substantial risk to progress to secondary acute myeloid leukemia (sAML)." (PMID 36814396, 2023). "Primary myelofibrosis (PMF) is a rare myeloproliferative neoplasms (MPN) characterized by mutations in three driver genes that cause an hematopoietic stem cell – derived monoclonal proliferation: janus kinase 2 (JAK2), calreticulin (CALR) or MPL proto-oncogene (MPL)." (PMID 37822925, 2023). "The myeloproliferative neoplasms (MPN) are usually sporadic diseases characterized by increased JAK/STAT pathway signaling due to a somatic driver mutation in either the JAK2, CALR, or MPL gene." (PMID 34209587, 2021). "Mutations of JAK2V617F, CALR, and MPL genes confirm the diagnosis of myeloproliferative neoplasm (MPN)." (PMID 34300032, 2021). "Myeloproliferative neoplasms (MPN) are clonal hematologic malignancies with dysregulated myeloid blood cell production driven by JAK2, calreticulin, and MPL gene mutations." (PMID 34680185, 2021). "Myeloproliferative neoplasms (MPN) are a group of clonal malignant bone marrow (BM) diseases, originating from a hematopoietic stem cell (HSC) which acquired a MPN phenotypic driver mutation (i.e., in JAK2, CALR, or MPL), leading to constitutively active JAK-STAT signaling." (PMID 32983162, 2020). "Essential thrombocythemia (ET) is a myeloproliferative neoplasm (MPN) derived from clonal expansion of hematopoietic progenitor cells carrying a mutation in the cytokine receptor/JAK2-signaling pathway (JAK2, CALR, or MPL)." (PMID 29515972, 2018).
myeloproliferative neoplasm (continued). "First, formation of a mutant calreticulin is the critical lesion in up to half the patients with myeloproliferative neoplasms, MPN, and nearly all of the rest are due to a Jak2 activating mutation." (PMID 30097573, 2018). "The human CALR gene is encoded on chromosome 19, which is prone to genomic alterations in abnormal neutrophils isolated from SLE patients, and somatic insertion/deletion mutations in exon 9 of calreticulin have been identified in myeloproliferative neoplasms with non-mutated JAK2 kinase." (PMID 27483354, 2016). "Calreticulin (CALR) mutations present the main oncogenic drivers in JAK2 wildtype (WT) myeloproliferative neoplasms (MPN), including essential thrombocythemia and myelofibrosis, where mutant (MUT) CALR is increasingly recognized as a suitable mutation-specific drug target." (PMID 36813992, 2023). "JAK2V617F and Calreticulin (CALR) mutations are the most frequent molecular causes of Phi-negative myeloproliferative neoplasms (MPN)." (PMID 36908768, 2023). "Another study identified ERp57/PDIA3 as being indirectly involved, with a mutant calreticulin gene (CALR), in altered Ca2+ mobilization in patients with myeloproliferative neoplasms." (PMID 35109791, 2022). "Discovery of somatic mutations in the calreticulin gene (CALR) has identified a subgroup of Philadelphia-negative chronic myeloproliferative neoplasms (MPN) with separate haematological characteristics and prognosis." (PMID 27764253, 2016). "This is exemplified by the recent discovery that patients with myeloproliferative neoplasms (MPNs) that did not have a janus kinase 2 (JAK2) mutation (a mutation occurring in the vast majority of patients) are characterized by somatic mutations in their calreticulin gene." (PMID 25688334, 2015). "Calreticulin (CALR) mutations have recently been reported in 70–84% of JAK2V617F-negative myeloproliferative neoplasms (MPN), and this detection has become necessary to improve the diagnosis of MPN." (PMID 26501981, 2015). "Primary myelofibrosis (PMF) is a clonal myeloproliferative neoplasm (MPN) stemming from hematopoietic stem and progenitor cells (HSPCs), frequently associated with mutations in Janus kinase signal transducer (JAK2), calreticulin (CALR), or thrombopoietin receptor (MPL)." (PMID 41268532, 2025). "Myelofibrosis (MF) is a rare BCR-ABL negative myeloproliferative neoplasm characterized by clonal proliferation of stem cells, with mutations in JAK2, CALR, or MPL genes." (PMID 38983933, 2024). "Mutations in JAK2, CALR, and MPL are major disease drivers for myeloproliferative neoplasm (MPNs), and can initiate or promote MPNs with or without other co-mutations." (PMID 39682303, 2024). "Myeloproliferative neoplasms (MPN) include chronic myeloid leukemia (CML), the JAK2/MPL/CALR-associated MPN (essential thrombocythemia, primary myelofibrosis, and polycythemia vera), chronic neutrophilic leukemia (CNL), chronic eosinophilic leukemia, and MPN-NOS/unclassifiable." (PMID 39075565, 2024). "In contrast, the presence of JAK2, CALR, or MPL mutations in the absence of SF3B1 should orient the diagnosis to a myeloproliferative disorder." (PMID 37370785, 2023). "This study was conducted to evaluate the frequency of JAK2, CALR, and MPL mutations in BCR-ABL negative myeloproliferative neoplasms and their association with demographic data and hematologic parameters in a referral center, in the Middle East." (PMID 33936230, 2021). "Seventy-one patients with BCR-ABL negative myeloproliferative neoplasms were evaluated for JAK2 V617F, CALR type 1, CALR type 2, and MPL by allele-specific PCR and conventional PCR from 2018 to 2019." (PMID 33936230, 2021). "Notably, one of the mutations driving the myeloproliferative neoplasm (MPN) development is that of the calreticulin-encoding CALR gene; this mutation activates MPL/JAK/STAT signaling in MPN stem cells, thereby promoting better survival and expansion outside the bone marrow niche." (PMID 32268506, 2020).